ERG (ETS transcription factor ERG)
Description:
Transcriptional regulator. May participate in transcriptional regulation through the recruitment of SETDB1 histone methyltransferase and subsequent modification of local chromatin structure.
Synonyms: erg-3; p55; LMPHM14
Tractability: Small molecule: a structure with a bound ligand is known; a high-quality ligand is known; it belongs to a druggable protein family. PROTAC: UniProt records ubiquitination sites on it; ubiquitination databases record sites on it; a small molecule that binds it is known.
Target class: Transcription factor
Gene: Protein-coding gene on chromosome 21 (38,380,027 to 38,661,780, reverse strand). Ensembl gene ENSG00000157554.
Subcellular location: Nucleus; Cytoplasm
Subcellular location (Human Protein Atlas): Nucleoplasm; Cytosol
Gene Ontology:
Molecular function: DNA-binding transcription activator activity, RNA polymerase II-specific; protein binding; RNA polymerase II cis-regulatory region sequence-specific DNA binding; sequence-specific double-stranded DNA binding; DNA binding; DNA-binding transcription factor activity, RNA polymerase II-specific; chromatin binding; DNA-binding transcription factor activity; sequence-specific DNA binding
Biological process: positive regulation of transcription by RNA polymerase II; cell differentiation; protein phosphorylation; regulation of transcription by RNA polymerase II; signal transduction; regulation of DNA-templated transcription
Cellular component: cytosol; nucleoplasm; ribonucleoprotein complex; chromatin; nucleus; cytoplasm
Genetic constraint (gnomAD): Loss-of-function variants: 5 observed, 44.84 expected, observed/expected ratio (o/e) 0.11, 90% interval 0.057 to 0.23. The upper end of that interval is the gene's LOEUF score, 0.23, which puts it in group 1 of 6, group 1 being the genes least tolerant of losing a copy. Missense variants: 408 observed, 605.83 expected, observed/expected ratio (o/e) 0.67, 90% interval 0.62 to 0.73. Synonymous variants: 213 observed, 234.27 expected, observed/expected ratio (o/e) 0.91, 90% interval 0.81 to 1.02.
Cancer hallmarks: cell replicative immortality (promotes)
Homologues: Orthologues: chimpanzee ERG (99% identical), macaque ERG (99% identical), dog ERG (97% identical), rat Erg (97% identical), mouse Erg (96% identical), pig ERG (96% identical), rabbit ERG (96% identical), guinea pig ERG (96% identical), tropical clawed frog erg (90% identical), zebrafish erg (59% identical). Paralogues in human: FLI1 (63% identical), ETS1 (26% identical), ETS2 (26% identical), GABPA (25% identical), FEV (22% identical), ETV1 (18% identical), SPDEF (18% identical), ELF4 (17% identical), ETV5 (17% identical), ETV6 (17% identical), ELK4 (17% identical), ETV4 (17% identical), and 16 more.
Diseases named in the same sentence as ERG in open-access papers:
ERG is named in the same sentence as 226 diseases in open-access papers, as found by Europe PMC text mining. Sharing a sentence is not in itself a finding about the gene and the disease. The quoted sentences say what the papers report.
prostate carcinoma (838 papers, 2007 to 2026). A carcinoma that arises from epithelial cells of the prostate gland. "The over-expression of another TRP channel, TRPM4, which is robustly expressed in prostate cancers, was inversely associated with ERG fusions or the over-expression of ERG and other ETS family transcription factors." (PMID 40332161, 2025). "The two well-expressed channels of the super family, TRPML2 and TRPM4, have divergent associations with the most prevalent prostate cancer molecular aberrations, ERG fusions." (PMID 40332161, 2025). "A higher level of MTAP staining was linked to TMPRSS2:ERG fusion positive prostate cancers (p < 0.0001)." (PMID 40554389, 2025). "In contrast, prostate cancer cases with high TRPM4 mRNA expression were associated with lower ERG fusion frequency than cases with low TRPM4 mRNA expression." (PMID 40332161, 2025). "Studies have shown that Asian populations exhibit higher mutation rates of SPOP and FOXA1 in prostate cancer, while European populations are more characterized by ERG fusion mutations and PTEN loss." (PMID 39882449, 2024). "BAF complexes are required for ERG-mediated basal-to-luminal transition in prostate cancer organoids, a known hallmark of ERG activity in prostate cancer." (PMID 38914477, 2024). "Considering the well-established associations of PTEN (loss) and ERG (gain) with the outcomes and prognosis of prostate cancer patients, we attempted to investigate the prognostic relevance of LAMTOR4 in conjunction with PTEN or ERG." (PMID 39125671, 2024). "With prostate cancer now the leading cause of cancer-related death among men in Uganda, there is a need to further understand the role of the ERG gene and confirm its prevalence." (PMID 38730435, 2024). "The most common molecular alteration in prostate cancer is the fusion of ERG and TMPRSS2, a widespread event associated with poor prognosis." (PMID 39351232, 2024). "To gain insight into how ERG translocations cause prostate cancer, we performed single cell transcriptional profiling of an autochthonous mouse model at an early stage of disease initiation." (PMID 38585869, 2024). "In contrast, PTEN loss and ERG gain are considered as biomarkers of aggressive prostate cancer phenotype." (PMID 37345203, 2023). "The presence of the TMPRSS2::ERG fusion in prostate cancer is associated in part with cancer recurrence, and commonly corresponds to a more aggressive malignancy and overall poorer clinical prognosis." (PMID 37509339, 2023). "The exact molecular mechanisms underlying the pathogenic role of TMPRSS2: ERG fusion in prostate cancer are yet to be fully uncovered, but there is evidence suggesting its association with the clinical course of the disease." (PMID 37185705, 2023). "A few years ago, a meta-analysis demonstrated that ERG overexpression or positive fusion status was associated with the advanced pathological characteristics of patients with prostate cancer." (PMID 37511059, 2023). "On the contrary, PTEN heterogeneous loss was statistically linked with ERG negativity, which was in turn related to high-grade prostate carcinomas." (PMID 37185705, 2023). "In the current study, we demonstrated that homogeneous PTEN loss was associated with immunohistochemical ERG positivity; the latter being mostly linked to low-grade prostate carcinomas." (PMID 37185705, 2023). "Prostate cancers with ERG driver mutations (n=85), mutually exclusive to SPOP (OR=0.102, 95% CI, 0.002–0.725, p=0.013;), were evenly distributed among the remaining prostate cancers in MuAt clustering." (PMID 37420249, 2023). "The identification of the TMPRSS2:ERG fusion as a frequent molecular alteration occurring in nearly half of prostate cancer cases has revolutionized our comprehension of the underlying mechanisms driving this malignancy." (PMID 37511059, 2023). "Meanwhile, the positive expression of ERG proved to be significantly associated with a homogeneous loss (score 0) of PTEN in prostate cancer." (PMID 37185705, 2023).
prostate carcinoma (continued). "The TMPRSS2:ERG fusion is considered relevant to prostate cancer, but its association with the development and progression as well as its clinical significance have not been fully elucidated." (PMID 37511059, 2023). "ERG (E-26 transformation-specific-related gene) is another gene implicated in AR-signaling in prostate cancer through microtubule depolymerization." (PMID 35884386, 2022). "The prognostic relevance of the most common mutations in prostate cancer, involving ERG and other ETS genes, is still unclear." (PMID 35574900, 2022). "The specificity of this gene rearrangement in prostate cancer allows ERG evaluation by IHC to be of diagnostic value in both primary and metastatic tumors originating from the prostate." (PMID 35513774, 2022). "Full-length ERG and several truncated ERG variants detected in prostate cancer contain in the N-terminus a KGGK motif acetylated by the acetyltransferase p300." (PMID 35267426, 2022). "Recurrent fusions at the TMPRSS2 5′ UTR (untranslated region) to ETV1 (ETS variant transcription factor 1) or ERG (ETS-related gene) lead to outlier expression and drive progression of prostate cancer." (PMID 36364238, 2022). "Since TMPRSS2 is an androgen-dependent gene, the fusion protein encoded by TMPRSS2/ERG is overexpressed in prostate cancer, which contributes to tumor progression." (PMID 35954308, 2022). "Dysregulation of alternative splicing in prostate cancer is linked to transcriptional programs activated by AR, ERG, FOXA1, and MYC." (PMID 36170835, 2022). "Fusion events other than the TMPRSS2:ERG are also associated with the regulation of lncRNAs in prostate cancer." (PMID 33634124, 2021). "A gene fusion in prostate cancer, causes the overexpression of oncogenic ERG resulting in changes in chromatin organization and territories encompassing genes associated with aggressive prostate cancer." (PMID 34422840, 2021). "The consequent upregulation in transcriptional activity of ERG is associated with prostate tumorigenesis and is responsible for increased invasiveness of prostate cancer cells in metastatic disease." (PMID 34638309, 2021). "Meanwhile, the TMPRSS2: ERG fusion gene has been associated with prostate cancer and serves as a biomarker for the diagnosis and stratification of androgen-sensitive prostate cancer." (PMID 34063247, 2021). "In prostate cancer, recurrent gene fusions involving the ERG transcription factor and point mutations in the ubiquitin ligase adaptor SPOP are two truncal mutations that are mutually exclusively distributed across tumor genomes 3–9." (PMID 33531470, 2021). "Recent research also showed that miR-223-5p targets ERG (encoding ETS transcription factor ERG) and inhibited prostate cancer cell proliferation and migration." (PMID 34457026, 2021). "In prostatic cancer, the expression of ERG was positively associated with CD204+ and CD3+ cell infiltration." (PMID 34489925, 2021). "In a later investigation, it was shown that several other prostate cancer-associated lncRNAs or PCATs are correlated with ERG expression and are significantly down-regulated by ERG knock-down in both VCaP and DuCaP cells." (PMID 33634124, 2021). "Among other cancers, prostate cancer is known to be driven by TFs such as ERG, and SOX2 has been implicated as well." (PMID 33613844, 2021). "One of the examples is the ERG oncogene that causes overexpression of nicotinic acetylcholine receptors (nAChRs) in prostate cancer cells which in turn, under nicotine treatment, induces tumor cell proliferation." (PMID 32316383, 2020). "Among molecular defined prostate cancer cases, 452 (48%) prostate cancers were ERG fusion positive, 109 (14%) prostate cancers were PTEN loss." (PMID 32467600, 2020).
prostate carcinoma (continued). "Most deletions in prostate cancer are either linked to an ERG-positive (3p, 8p, PTEN, 12q, 16q, 17q) or ERG-negative status (5q, 6q, 13q, 18q)." (PMID 32417965, 2020). "CTCF staining was strongly linked to TMPRSS2:ERG rearrangement and ERG positivity in our set of prostate cancers (P < 0.0001)." (PMID 31736271, 2020). "Based on genomic profiles, prostate cancer can be divided into seven molecular subtypes which bear distinct oncogenic drivers including fusions with ETS family members (ERG, ETV1, ETV4, and FLI1) and mutations in SPOP, FOXA1, and IDH1." (PMID 33273988, 2020). "Most chromosomal deletions in prostate cancer are linked either to cancers harboring ERG fusions (3p, 8p, PTEN, 12q, 16q, 17p) or to the ERG-negative subset (5q, 6q, 13q, 18q)." (PMID 32417965, 2020). "A study of a cohort of 333 primary prostate carcinomas showed that 74% of these tumors fell into one of seven subtypes of a molecular taxonomy defined by specific gene fusions (ERG,ETV1/4 and FLI1) or mutations (SPOP,FOXA1 and IDH1)." (PMID 33058520, 2020). "An earlier study of a cohort of 333 primary prostate carcinomas showed that 74% of these tumors fell into one of seven subtypes of a molecular taxonomy defined by specific gene fusions (ERG, ETV1/4 and FLI1) or mutations (SPOP, FOXA1 and IDH1)." (PMID 33058520, 2020). "PRMT5 methylation of the TMPRSS2:ERG fusion protein is commonly seen in prostate cancer (PC) and implicated in prostate tumor formation by inhibiting AR -dependent transcription." (PMID 32743345, 2020). "At present, there are no studies of TDRD1 in OC however, TDRD1 is now considered a potential biomarker for prostate cancer as it strongly associates with expression of the frequently mutated transcription factor, ERG." (PMID 33374923, 2020). "Next to TMPRSS2:ERG fusions, genomic deletions at various chromosomal loci represent the most prevalent recurrent genetic alterations in prostate cancer where specific mutations of cancer genes are rare." (PMID 32377272, 2020). "Significant association of ERG protein expression with gleason score and perineural invasion signifies its prognostic significance in prostatic carcinoma." (PMID 30658688, 2019). "Loss of CHD1 has been implicated in the initiation of ETS prostate cancers, preventing ERG rearrangement in the prostate and thus explaining the exclusivity between ETS positivity and homozygous loss of CHD1." (PMID 31366128, 2019). "We recently used these GEM models with prostate-specific expression of ERG (Pb-Cre4; Rosa26ERG/ERG) with and without PTEN deletion to examine the mechanisms underlying tumor progression in ERG-fusion positive prostate cancers." (PMID 31143708, 2019). "High-level nuclear ELAC2 staining was associated with TMPRSS2:ERG rearrangement and ERG expression in prostate cancers (p< 0.0001 each)." (PMID 31452838, 2019). "The rate of PTEN loss was significantly lower in AA compared to EA prostate cancer, similar to the lower rate of ERG expression." (PMID 31826177, 2019). "TRPM8 variant α is generally overexpressed in prostate cancer but contrary to this our data show that it is suppressed in ERG over-expressing LnTE3 cells." (PMID 31303963, 2019). "SNW1 expression was strongly linked to TMPRSS2:ERG rearrangement and ERG expression in our set of prostate cancers." (PMID 31043167, 2019). "In a relevant number of human prostate cancers, ERG gene fusion occurs concomitantly with PTEN loss." (PMID 31143708, 2019). "SPOP mutations and ERG rearrangements show near complete mutual exclusivity across multiple independent cohorts representing thousands of prostate cancer samples." (PMID 29202479, 2018). "The level of BCAR1 staining was associated with the presence of ERG rearrangements and ERG expression in prostate cancers (p < 0.0001 each)." (PMID 29304771, 2018).
prostate carcinoma (continued). "Much work has been done on elucidating the mechanism by which ERG is associated with prostate cancer." (PMID 29342271, 2018). "At the cellular level, DB1255 altered ERG-controlled transcription on artificial promoter and on osteopontin promoter, an ERG-driven promoter associated with prostate cancer." (PMID 29921764, 2018). "Our present association results showed that overexpressions of both ERRα and ERG were closely associated with higher Gleason scores and metastasis in prostate cancer patients." (PMID 30042415, 2018). "Further analysis of the association between ERRα and ERG expressions in ARlow and ARhigh subsets of prostate cancer patients in the same datasets revealed that both ERRα and ERG exhibited a positive correlation in both subsets of patients." (PMID 30042415, 2018). "The proto-oncogene ERG is a regulator of hematopoiesis, including B-cell development, and is implicated in the pathogenesis of Ewing sarcoma, prostate cancer, and acute myeloid leukemia." (PMID 29330417, 2018). "Previous studies have described PTEN loss as a subclonal event after ERG gene fusion within a given established prostatic carcinoma clone." (PMID 29088771, 2017). "Since then, genome-wide studies have inferred potential regulatory cooperativity between AP1 and other ETS factors such as ELK1 and ERG and in the latter case this association is thought to be important for the context of prostate cancer." (PMID 28859074, 2017). "Using the same TMA as in our current study, we earlier found that overexpression of other DSB repair genes such as NBS136 and LIG437 were also linked to ERG-activation in prostate cancer." (PMID 28515422, 2017). "The same study also showed that βIII-tubulin expression is strongly associated with ERG expression and TMPRSS2:ERG rearrangement in prostate cancer." (PMID 28677634, 2017). "High-level GGH staining was linked to TMPRSS2:ERG rearrangement and ERG positivity in prostate cancers." (PMID 28146062, 2017). "Alternative splicing patterns of an androgen-regulated oncogenic fusion gene called ETS-related gene (ERG) are associated with more advanced forms of prostate cancer progression." (PMID 28382513, 2017). "The comparison of FAM13C with established molecular features in prostate cancer demonstrated that increased FAM13C expression is strongly associated with the subset of tumors harboring the TMPRSS2:ERG gene fusion." (PMID 28415558, 2017). "Almost all chromosomal deletions occurring at relevant frequency are strongly linked to either ERG-positive or ERG-negative prostate cancers." (PMID 27861151, 2016). "Depletion of ERG by RNAi decreases proliferation and/or invasiveness in prostate cancer cell lines, and ectopic expression of ERG in aged mice or in concert with loss of tumor suppressors in younger mice promotes prostate carcinogenesis." (PMID 27626314, 2016). "In this study, we found that, out of 369 miRNAs, the expression levels of four miRNAs, including three members of the miR-200b subfamily and miR-205, are positively associated with ERG expression in MSKCC prostate cancer data sets." (PMID 27191272, 2016). "The strong inverse association with TMPRSS2:ERG fusions identifies 6q15 deleted cancers as a significant subgroup among “non fusion-type” prostate cancers." (PMID 26684029, 2016). "Since these two types of genetic alterations, i.e., SPOP mutations and TMPRSS2-ERG fusions, similarly lead to ERG stabilization, it is conceivable that their incidences are mutually exclusive in prostate cancers." (PMID 27200299, 2016). "Overall, our study demonstrates that SENP1 overexpression is frequent in ERG positive prostate cancer and linked to PTEN deletions." (PMID 26202067, 2015). "In summary, these data identify 12p deletion as a frequent event in prostate cancer, which is unrelated to the ERG fusion status but strongly linked to aggressive tumor behavior." (PMID 26293672, 2015).